GLI1 (GLI family zinc finger 1)
Diseases named in the same sentence as GLI1 in open-access papers (continued):
Sharing a sentence is not in itself a finding about the gene and the disease.
tumor (continued). "This analysis revealed a positive correlation between CCL20 and GLI1 expressions (r = 0.39, p < 0.01) via Spearman correlation, suggesting that GLI1 and CCL20 may be functionally linked in HCC tumours." (PMID 40913253, 2025). "Next, the expressions of PKA and GLI1 were checked in the normal and tumor tissues." (PMID 39880092, 2025). "In pancreatic ductal adenocarcinoma (PDAC), its circular RNA isoform, circNEIL3, acts as an oncogenic driver by sponging the tumour-suppressive miR-432-5p, thereby promoting the ADAR1-mediated editing of GLI1 and facilitating tumour proliferation and metastasis." (PMID 40724564, 2025). "However, the promoter at the 5’ end of the GLI1 gene is replaced by the highly active promoter of the fusion partner, which results in elevated expression of GLI1 and subsequent activation of downstream gene transcription, thereby promoting tumor development." (PMID 39995845, 2025). "The xenograft model was conducted to establish the effect of Gli1 on tumor angiogenesis and growth." (PMID 38493151, 2024). "In tumor cells, GLI1 promotes cell proliferation, inhibits apoptosis, enhances cell migration and invasion, and participates in the occurrence and development of tumors by regulating the tumor microenvironment and inducing angiogenesis." (PMID 38741887, 2024). "Likewise, immunohistochemistry analysis of clinical MBSHH sections indicated GLI1 and p-GLI1were abundantly expressed in the nuclei and cytosol of tumor cells, respectively." (PMID 38307877, 2024). "In addition, GLI1 blockade effectively attenuated EHF upregulation in tumor cells and immunosuppressed animal models, thereby reducing CCA cell proliferation and growth." (PMID 38741887, 2024). "Moreover, Spearman correlation analyses conducted on tumor tissues obtained from TCGA demonstrated significant positive correlations between GLI1 and GLI2 in 30 tumor tissues, with only one tissue showing a significant negative correlation." (PMID 38498906, 2024). "Interestingly, most of the positive staining was detected in the epidermis overlying or bordering the tumor mass, while the tumor mass had strong staining only in a smaller proportion of samples for GLI1 and GLI3." (PMID 38892279, 2024). "The combination of GLI1 IHC and p16 stain is superior in detecting GLI1 amplified neoplasms." (PMID 38491228, 2024). "Taken together, these results indicate that Gli1 may promote tumor angiogenesis by positively regulating bFGF expression." (PMID 38493151, 2024). "Stromal AR signaling, particularly within Gli1-lineage cells, may significantly contribute to therapy resistance by supporting epithelial cell survival and tumor growth during ADT." (PMID 39369165, 2024). "The pivotal role of GLI1 in mediating the anti-tumor effects of α-mangostin was further underscored by the attenuation of a-smooth muscle actin (α-SMA) expression in PSCs upon GLI1 knockdown, highlighting the intricate molecular mechanisms underlying α-mangostin’s anti-angiogenic properties." (PMID 39595559, 2024). "We speculate that this may be due to the fact that the oncogenic effect of GLI1 mainly occurs within tumor cells, and there may be mechanisms of intercellular interactions when studying the tumor microenvironment." (PMID 38741887, 2024). "Similar analyses carried out on tumor cell lines indicated that GLI1 and GLI2 were significantly positively correlated in 15 of the tested cell lines, while GLI1 and GLI3 exhibited significant positive correlations in 6 cell lines, but a negative correlation in 1 cell line." (PMID 38498906, 2024). "GLI1 enhances tumor drug resistance through inducible glucuronidation." (PMID 38498906, 2024). "Finally, we also showed that therapeutic blockade of Gli1 using GANT-61 obviously suppressed tumor angiogenesis." (PMID 38493151, 2024). "In tumor tissue, GLI1 IHC staining exhibits moderate to strong intensity." (PMID 38498906, 2024).
tumor (continued). "Because aberrant IGF1 and Wnt activation has been shown to directly induce prostate oncogenesis and PCa development, these findings implicate stromal AR in Gli1-lineage cells acting as tumor niches to support prostate epithelial oncogenesis through IGF1/Wnt activation." (PMID 39369165, 2024). "In addition, GLI1 appears to regulate tumor progression and metastasis by mediating components of TMIE." (PMID 39483334, 2024). "When comparing the expression of GLI1 to other target proteins in the same location (tumor vs. tumor, border vs. border, and central vs. central), there is generally a stronger correlation in the locations of the epidermal layer than the tumor mass." (PMID 38892279, 2024). "Furthermore, GLI-1 has been found to correlate with tumor size, cellular differentiation, capsular integrity, and portal vein invasion." (PMID 38730691, 2024). "As angiogenesis is necessary for tumor metastasis, we speculate that Gli1 may be involved in the angiogenesis process in NSCLC." (PMID 38493151, 2024). "However, although RAS signalling activation is frequent in ERMS tumours, RAS oncogenic mutations (HRAS, KRAS, and NRAS) inhibit GLI1 through the MEK/ERK pathway." (PMID 36765685, 2023). "Additionally, genomic amplification of chromosomal region 12q13-15 containing the GLI1 gene was identified in a very small subset of ARMS tumours." (PMID 36765685, 2023). "To investigate whether Gli1 upregulation promotes tumor progression of PDAC cell lines, we first examined Gli1 expression by qRT-PCR and Western blotting in five PDAC cell lines." (PMID 38041128, 2023). "Additionally, Sonidegib and Vismodegib exhibited dose- and exposure-dependent inhibition of GLI1 in tumour and normal skin biopsies." (PMID 36765685, 2023). "Overexpression of Gli1 can accelerate the proliferation of subcutaneous tumors in mice and is closely related to the density of nerve plexuses, while downregulating circ-RNA inhibits tumor proliferation and reduces the density of nerve plexuses." (PMID 38041128, 2023). "In addition, AIM2 inhibited Gli1 expression through the smoothened homolog (SMO)‐independent pathway and regulated tumor cell proliferation and migration in a Gli1‐dependent manner." (PMID 36161280, 2023). "Indeed, increasing evidence has revealed a tumor suppressor role of Itch through antagonizing the activation of the Gli1-dependent Hh signaling pathway." (PMID 38097536, 2023). "It is suggested that growth factors, including SHH, produced by tumor cells paracrinely induce Gli1 and Gli2 expressions in tumor vascular endothelial cells, and various angiocline factors produced by tumor vascular endothelial cells induce SHH and Gli1 in tumor cells." (PMID 37240209, 2023). "In other words, RCC2 promotes tumor growth by promoting Gli1." (PMID 38008751, 2023). "The identification of these GLI1-expressing fibroblasts as the source of neoplasia in vitro might represent one of the fundamentals of this biological process." (PMID 38060571, 2023). "Similarly, Vasohibin 2 (VASH2) protein suppresses pancreatic CSCs through decreasing SMO and Gli1/2, while also functioning as a tumor promoter, stimulating resistance to doxorubicin (DOX) upregulating pancreatic CSCs via the Hh and Notch pathways." (PMID 37305676, 2023). "Co-amplification of Gli1 and Gli2 occurs frequently in malignancy, but dependence on Gli1 or Gli2 varies between cancers, between subtypes, and between cell lines of the same subtype; Hh may even be activated heterogenously within the tumor microenvironment." (PMID 37954979, 2023). "While hinokitiol reduces the expression of both UHRF1 and GLI1, it remains unclear whether the tumor-suppressing function of hinokitiol is solely dependent on UHRF1 inhibition." (PMID 37380646, 2023). "We hypothesized that GLI1 activates RNA Pol I in response to irradiation and licenses the emergence of a radioresistant tumor population." (PMID 37380890, 2023).
tumor (continued). "We postulated that GLI1 would provide a survival advantage to irradiated tumor cells." (PMID 37380890, 2023). "Additionally, there are dichotomous modulators such as DYRK1A, which depending on tumour type, can stimulate the Hh pathway by promoting the nuclear translocation of GLI1 or induce its degradation by acting negatively on the cytoskeleton." (PMID 36765685, 2023). "On the other hand, Genistein, the other GLI clinically tested inhibitor, is a natural phytoestrogen with a wide variety of pharmacological properties; it is being extensively studied for its potential anti-tumour effects, affecting different pathways, among which, GLI1 signalling regulation." (PMID 36765685, 2023). "Moreover, UHRF1 functions as an epigenetic regulator, the depletion of which reprograms liver CSCs toward differentiation and tumor suppression via Hedgehog/GLI1 and Wnt signaling." (PMID 37380646, 2023). "In addition, the upregulation of USP44 delayed tumor growth and lung metastasis while the introduction of mutant Gli1 attenuated the suppression of tumor growth and metastasis mediated by USP44 overexpression." (PMID 38097536, 2023). "All Hh-dependent tumours have been found to display increased Gli1 expression." (PMID 36457847, 2022). "For example, topical CUR-61414, vitamin D3 and itraconazole reduced Gli1 levels and decreased tumor size in murine preclinical studies, but when the drugs went into clinical trials, none of the patients responded to treatment (and NLM, NCT02735356 and NCT01358045)." (PMID 36430669, 2022). "Taken together, these results demonstrate a promotional role of stromal AR signaling in Gli1-lineage cells to support prostatic epithelial oncogenesis and tumor development, which also provides experimental evidence to use these relevant models for in-depth molecular analyses." (PMID 36323713, 2022). "Meanwhile, it was verified that the suppression of GLI1 protein could evoke anoikis in vitro and prevent tumor formation in vivo." (PMID 36685842, 2022). "Gli1 activity is relevant to tumor aggressiveness in papillary thyroid carcinoma." (PMID 36517618, 2022). "Furthermore, treatment with a MKL1 inhibitor, CCG-1423, reduced GLI1 expression and decreased tumor burden in drug-resistant BCC cells in cell culture and in vivo." (PMID 36010600, 2022). "In pancreatic cancer, SHh indirectly promotes tumor angiogenesis by inducing Ptch1 and Gli1, thereby inhibiting two enriched stroma-derived antiangiogenic factors (THBS2 and TIMP2), and directly promotes tumor angiogenesis by activating small GTPases of the RHO family in the presence of VEGF." (PMID 36517618, 2022). "As in the preclinical studies, biological response is estimated by GLI1 mRNA expression, whereas clinical response is based on both objective and subjective measures e.g., changes in tumor volume, versus visually determined tumor clearance." (PMID 36430669, 2022). "In addition to DYRKi, the MKL1 inhibitor CCG-1423 was reported to inhibit the tumor growth and GLI1 expression in SMO inhibitor-resistant cell lines." (PMID 35163655, 2022). "The results showed that tumor tissues from EGFR TKI-resistant patients had significantly increased GLI1, SMO, BCL2, and SNAIL protein levels compared with those from TKI-sensitive cases, suggesting that these proteins are possibly related to TKI resistance in NSCLC." (PMID 35154464, 2022). "Another critical factor for EWSR1-FLI1-mediated tumor development is GLI1." (PMID 35740349, 2022). "One strategy for inhibiting Shh signaling in tumor growth is by inhibiting Gli1 levels." (PMID 36531063, 2022). "Although most literatures indicate that Hedgehog signaling positively regulates the EMT program and tumor progression, the contrary findings were also reported that describe that Gli1 binds with the promoter of E‐cadherin to activate its transcription, thereby inhibiting EMT." (PMID 35601657, 2022).
tumor (continued). "Since GLI1 mRNA and protein where negatively correlated with SETD7 expression, it is possible that tumour-suppressing effects of SETD7 could be mediated by reducing GLI1 expression." (PMID 35326563, 2022). "Increased expression of SMO and GLI1 was directly correlated to a larger tumor size." (PMID 33440657, 2021). "However, and in contrast to its function in some other cancer types, Hedgehog signaling and its transcription factor GLI1 exert tumor-suppressive functions in NB, rendering GLI1 an interesting new candidate for anti-NB therapy." (PMID 33921042, 2021). "Materials and methods: Immunohistochemistry, western blotting and qRT-PCR assay were performed to analyze and compare the expression of GLI1 in OS tumor tissue and normal bone tissue as well as in cisplatin sensitive and resistant cell lines (SOSP-9607 and SOSP-9607/CR)." (PMID 34659557, 2021). "Additionally, lower expression of PTCH1 was positively correlated with increased nuclear GLI1 in both normal epithelium and tumor samples." (PMID 34572373, 2021). "In addition, GANT61, a inhibitor of Hedgehog pathway was used in xenograft tumor model to further verify the effect and mechanism of GLI1 on cisplatin resistance in OS." (PMID 34659557, 2021). "In HNSCC, Gli1 is often upregulated at the tumor-stroma intersection, which gets further augmented following irradiation, where it contributes to stromal-mediated radio-resistance of the tumor." (PMID 33968932, 2021). "Moreover, GLI1 is also highly expressed in HCC tumor tissues and liver CSCs, and TOP1 expression levels positively correlate with the metastasis, recurrence and survival of HCC patients." (PMID 34649567, 2021). "The sphere-forming efficiency, as well as the average volume of the formed spheres, were significantly decreased in GANT-61-treated cells, suggesting GLI1 inhibitors may act to attenuate tumor formation during KS initiation or progression." (PMID 34422814, 2021). "Noteworthy, Gli1 participates in enhancing CSCs features and mediating tumor progression." (PMID 34769099, 2021). "While Hedgehog-GLI1 pathway regulates tumor resistance via distinct mechanisms 16, 17, it remains unclear whether the pathway plays an important role in the resistance of OS." (PMID 34659557, 2021). "Similarly, nuclear protein expression of Gli1 and NF-κB p65 was significantly enhanced in tumor tissues from SW1990 cells treated with IL-1β, TNF-α and Shh, whereas no significant expression was observed in the tissues from BxPC-3 cells." (PMID 34046348, 2021). "They demonstrated that GLI1, that is upregulated at the tumor-stroma intersection in HNSCC, is increased by RT, where it contributes to stroma-mediated resistance, and that HH inhibition offers a rational strategy to reverse this process and to sensitize HNSCC to irradiation." (PMID 34307351, 2021). "We propose that Rack1‐mediated Gli1 signaling and cell cycle activation in MB tumor cells might be essential for SHH‐MB tumorigenesis." (PMID 34480519, 2021). "Therefore, it is likely that these GLI1-rearranged fusion genes activate Shh signaling through the increased expression of GLI1, supporting the involvement of PTCH1-GLI1 fusion in tumor development." (PMID 34131151, 2021). "We found that GLI1 KO dramatically inhibited xenograft tumor growth in CSCs." (PMID 34649567, 2021). "We found that GLI1 was highly expressed in tumor tissues, liver CSCs and oncosphere cells." (PMID 34649567, 2021). "Hh signaling molecules, such as ligands (SHh), receptors (PTCH1) or transcription factors (GLI1/2) in the tumor tissue or body fluid, may reflect tumor progression, metastasis, drug sensitivity or treatment response." (PMID 33440657, 2021).
tumor (continued). "An improved clinical response, including one CR, was also observed in three out of ten evaluable triple-negative advanced breast cancer patients with high paracrine Hh Pathway Activation Signature (HPAS), characterized by high tumor epithelial Hh and stromal GLI1 expression." (PMID 34572373, 2021). "Consequently, aPKC-ι phosphorylated GLI1 Ser84, which, in turn, promoted its nuclear translocation to activate cytokine genes (CCL2, CCL5, and TNFα) involved in the recruitment of tumor-associated macrophages (TAMs)." (PMID 34572373, 2021). "In a phase I study in 33 patients with mBCC or laBCC, tumor GLI1 was overexpressed as compared with normal skin controls; skin biopsies showed that GLI1 expression was down-modulated more than 2-fold in 10 (77%) of 13 patients following treatment with vismodegib." (PMID 34966484, 2021). "Similarly, GLI1 was also expressed more in poorly differentiated tissues and was strongly correlated with tumor invasion and lymph node metastasis." (PMID 34572373, 2021). "Additionally, another LncRNA/mRNA binomial axis (GLI1‐AS/GLI‐1) has been reported to be epigenetically regulated (enriched histone H3K27me3) at bidirectional gene promoter sequences, involved in tumor cellular proliferation and in vivo xenograft tumor growth." (PMID 33433063, 2021). "In addition, combining chemotherapy which inhibits bulk tumor with Notch1 and GLI1 inhibitors that abrogate stemness display an excellent synergy in inhibiting AA-TNBC, hence providing a potent therapeutic option for abrogating TNBC in AA women." (PMID 34889737, 2021). "They inhibit both GLI1 and GLI2 causing a significant decrease in tumor growth." (PMID 33179013, 2020). "Higher Gli1 expressions were detected in tumor samples than in paired normal tissues." (PMID 31931858, 2020). "All these suggest that Shh/Gli1 is potential to be an anti-angiogenic target, but its role in tumor angiogenesis is still largely unknown." (PMID 32286274, 2020). "Immunoreactivity for GLI-1 was also detected in the base membrane of the tumor cells." (PMID 33374329, 2020). "Pan-cancer analysis of the correlation of GLI1 and GLI2 with 19,540 genes expressed in 30 tumor types revealed that GLI1 and GLI2 are mutually the most correlated genes, and that all HH and TGFB genes are in the top 20 percentiles of most correlated genes with GLI1 and GLI2, with one exception." (PMID 32879407, 2020). "GLI1 expression in GLI1-knockout PDAC cells leads to the recovery of tumor formation ability." (PMID 32859041, 2020). "Finally, we demonstrate proof-of-concept anti-tumor efficacy in a demonstrably 5-FU-resistant CRC xenograft model with a first-in-class direct GLI1 inhibitor, SRI-38832." (PMID 32185127, 2020). "In addition, Shh/Gli1 signaling pathway is vital for drug resistance in anti-tumor therapy and inhibition of Shh/Gli1 has been proved to remit drug resistance." (PMID 32286274, 2020). "We also noticed that the majority of patients exhibited high-GLI1 expression (201/256 patients), and when stratified according to the tumour-node-metastasis (TNM) staging, a significantly stronger association for the patients with TNM stages III and IV was found." (PMID 32814764, 2020). "Likewise, SHH expression was detected in the tumor epithelium of prostate cancer samples while GLI1 expression, was upregulated in the stromal compartment, again providing evidence of paracrine ligand-dependent signaling to facilitate cancer development." (PMID 32957513, 2020). "In addition, shRNA knockdown of GLI1 in all tested EAC cell lines reduced tumor cell viability and their ability to form colonies." (PMID 32913560, 2020). "Moreover, our further study revealed that Shh/Gli1 and its downstream signaling pathway contributed to pristimerin-mediated tumor angiogenesis." (PMID 32286274, 2020).